TLR2 (toll like receptor 2)
Diseases named in the same sentence as TLR2 in open-access papers (continued):
Sharing a sentence is not in itself a finding about the gene and the disease.
tumor (continued). "For example, TNF-α enhances leukocyte recruitment to inflammatory sites and promotes infiltration of cytotoxic T cells into the tumor vicinity and TLR2-mediated production of IL-12 and TNF-α by macrophages results in NK cell activation and induction of the adaptive immune response." (PMID 29588627, 2018). "In mice with hepatocyte-deletion of Pten, TLR4 but not TLR2 deficiency suppressed tumor growth as well as hepatic inflammation, in good agreement with the results of our study." (PMID 30034633, 2018). "Accordingly, we boldly speculate that a single protein core can competitively bind to the endogenous ligand of TLR2/4 in the tumour stroma to repress inflammation." (PMID 29435195, 2018). "Positive TLR2 expression in the tumor microenvironment is supposed as an indicator of activated immune surveillance against the altered epithelial cells, whereas TLR2 expression by malignant keratinocytes is suggestive of resistance to apoptosis as a prosurvival mechanism." (PMID 30774831, 2018). "Furthermore, dying-cell-derived HMGB1 activates the TLR2/PI3K/Akt pathways and induces the EMT program, which are important signaling events underlying radiotherapy-driven acceleration of tumor metastasis." (PMID 29615080, 2018). "We conclude that in the tumor microenvironment, products that stimulate TLR2 and inhibitory AR may contribute to OSCC progression in part by directly activating the MAPK ERK1/2 pathway in malignant cells." (PMID 29467931, 2018). "Interestingly, systemic administration of a synthetic BLP, a TLR1/TLR2 agonist, to mice with established lung carcinoma, melanoma, or leukemia, led to tumor regression and a long-lasting protective response against tumor re-challenge." (PMID 29765907, 2018). "Furthermore, heat shock protein 72 on tumor-derived EVs enhances STAT3 activation in MDSCs through toll-like receptor 2 (TLR2)." (PMID 29534557, 2018). "While TLR2 agonists have antitumor activity, tumor-supportive activities have also reported." (PMID 29593736, 2018). "The Toll-like receptor-2 (TLR-2) plays a significant role in tumor progression." (PMID 29230082, 2017). "In addition, injection of a TLR2-blocking antibody into gp130F/F mice reduced stomach size and tumor burden as well." (PMID 29230082, 2017). "Therefore, to investigate the role of TLR2 or TLR4 in BCG-dependent AMPs release in tumor cells, we generated stable TLR2 or TLR4 knockdown lines from T24 cells and confirmed the reduced expression of TLR2 or TLR4 by Western blotting." (PMID 28881802, 2017). "In light of our results, efforts in using TLR2 agonists to generate T cell-dependent anti-tumor responses need to consider that TLR2 stimulation can have an entirely opposite effect depending on whether the TCR is engaged or not." (PMID 28742882, 2017). "Consistently, the promotion effect of circulating B16F0 cells on the metastatic colonization of disseminated B16F1 cells was also suppressed by sTLR2 and sTLR4, further confirming that TLR2/4 ligands are the main inflammatory stimuli that are responsible for promoting tumor metastasis by CTCs." (PMID 28415700, 2017). "To explore the inflammatory stimuli from CTCs that stimulate G-CSF and IL-6 expression, we focused on the tumor cell-derived TLR2 and TLR4 (TLR2/4) ligands, since IL-37 could suppress TLR4 ligand-induced inflammatory response." (PMID 28415700, 2017). "On the other hand, our study also confirmed that the promoting effect of CTCs on tumor metastasis could be abrogated by either inhibiting the inflammatory response or blocking TLR2/4 signaling." (PMID 28415700, 2017). "Addition of the α-TLR2 mAb to the organoid cultures resulted in significant reduction of organoid sizes in all cell lines compared to the isotype control, indicating that constitutive activation of the receptor promotes tumor growth." (PMID 25846753, 2015).
tumor (continued). "Importantly, the activation of TLR2 confers a growth-promoting effect on these cells, and blockade of the receptor using a monoclonal antibody has a profound inhibitory effect on tumor growth in both in vitro organoid and in vivo xenograft models." (PMID 25846753, 2015). "It is thus possible to hypothesize that other members of the Hsp70 family, when released from infected or tumor cells in vesicles, can engage a TLR2 pathway, leading to IL-10 production in myeloid cells, and polarizing macrophages to an M2 phenotype." (PMID 25419575, 2014). "On the other hand, TLR2 signaling suppressed cancer development and assisted tumor regression." (PMID 25309546, 2014). "The macrophages differentiated from BMC of orlistat-administered mice showed characteristic features of M1 macrophage phenotype confirmed by expression of CD11c, TLR-2, generation of reactive oxygen species, phagocytosis, tumor cell cytotoxicity, production of IL-1,TNF-α and nitric oxide." (PMID 24349275, 2013). "The efficient-activation of DCs by combined TLR2/4-agonists led us to speculate that DC/tumor generated in the presence of combined TLR2/4-agonists would be more effective than conventional un-activated fusions." (PMID 23555011, 2013). "The Toll-like receptor 2 (TLR2)-driven tissue response may promote neoangiogenesis and tumour growth by mechanisms that are poorly understood." (PMID 23866094, 2013). "In this context, it is of interest that soluble BGN serves as a ligand for TLR4 and TLR2, which might explain some of the anti-tumor effects of BGN." (PMID 24223213, 2013). "Our study provides strong evidence that TLR2 may be targeted by miR-143 to overcome chronic inflammation and down-regulate tumour invasion and migration." (PMID 23866094, 2013). "Additionally, we detected higher TLR2 expression in poorly differentiated tumour cells (SW620 and HCT116) compared with well-differentiated tumour cells (SW480 and LS174T)." (PMID 23866094, 2013). "We recently find that the loss of toll-like receptor 2 (TLR2) activities promotes the diethylnitrosamine (DEN) induced hepatocellular carcinogenesis and tumor progression, which associates with an abundant accumulation of reactive oxygen species (ROS) and endoplasmic reticulum (ER) stress." (PMID 24098333, 2013). "To determine if versican V1 could be the soluble factor responsible for the TLR2/6 activation observed here we examined versican V1 expression levels in tumor cells co-cultured with macrophages." (PMID 23424670, 2013). "TLR2-mediated cancer growth appears to be an important factor in tumor progression." (PMID 22815694, 2012). "Toll-like receptor 2/6 (TLR2/6) signaling in tumor cells is of particular interest as it is regarded as one of the mechanisms of chronic inflammation but it can also mediate tumor cell immune escape and tumor progression." (PMID 22815694, 2012). "Recent studies have demonstrated that LLC cells-produced factors such as versican is necessary for tumor growth and metastasis, a process that depends on TLR2-mediated myeloid cell activation, where activation of NF-κB results in inflammatory factors TNFα, IL-6 production." (PMID 23284890, 2012). "The result showed a drastic reduction in tumor volume in mice treated with sh-TLR2 RNAi(B)." (PMID 22815694, 2012). "A drastic reduction in tumor volume was observed in mice treated with sh-TLR2 RNAi(B)." (PMID 22815694, 2012). "Taken together, these results indicated that Pam2 lipopeptides induce IL-10 both in vitro and in vivo in a TLR2-dependent manner, which might play a role in suppressing tumor immunity induced by Pam2 lipopeptides." (PMID 21533081, 2011). "An analysis of the TLR2 expression in various tumor cell lines was carried out in ourlaboratory." (PMID 22649707, 2011).
tumor (continued). "A recent study has documented that versican, a large extracellular matrix proteoglycan, can activate tumour-infiltrating myeloid cells through TLR-2 and its coreceptors TLR-6 and CD14 and elicit the production of proinflammatory cytokines including TNF-alpha that enhance tumor metastasis." (PMID 20652007, 2010). "Indeed, the difference in tumor development in TLR2−/− compared to WT mice was most prominent in the proximal colon." (PMID 20885960, 2010). "Given that these three molecules are implicated in partially overlapping yet distinct aspects of tumor progression, a combinatorial therapeutic strategy that simultaneously targets CSPG4, xCT, and TLR2 may represent a novel and more effective approach to disrupt multiple tumor-supportive mechanisms." (PMID 41375047, 2025). "Additionally, tumor cells undergoing enhanced glycolysis, which supports their proliferation, angiogenesis, and metastasis, release exosomes that boost glucose uptake through TLR2 and NF-κB pathways." (PMID 40028322, 2025). "Furthermore, the membrane protein Amuc_1100 of A. muciniphila has been demonstrated to enhance gut barrier function and reduce inflammation through TLR2 signaling, while also inducing the production of tumor cytotoxic cytokines such as IFN-γ and granzyme B to inhibit tumorigenesis." (PMID 39966840, 2025). "Therefore, we speculated that SUP3 repressed tumor growth via TLR2 signaling by the immune cells of the host." (PMID 41291775, 2025). "Based on the ability of UCVs to induce effective antigen-specific immune responses via the specific delivery of antigens to DCs in a TLR2-dependent manner, we investigated whether these characteristics are reflected as an improved efficacy in mouse tumor models." (PMID 39066478, 2024). "Similarly, anti-tumor effect generated through activation of TLR2 and 4, by OM-174 (CXR-526), a lipid A (Escherichia coli origin) derivative, is currently being evaluated as a vaccine adjuvant for the treatment of melanoma in phase I/II trials, in addition to a phase I trial against solid tumors." (PMID 37936697, 2023). "High mRNA level of TLR2 could accelerate tumor progression in LUAD." (PMID 37965055, 2023). "Moreover, the over‐expressed TLR2 colocalized with the tumor‐derived DNA in DCs." (PMID 37786300, 2023). "Furthermore, Hep1 cells localized in the invasive zone could secrete SAAs to regulate Formyl Peptide Receptor 1+ (FPR1+) macrophage recruitment and induce M2 polarization through SAAs-TLR2 axis, resulting in local immunosuppression and tumor progression." (PMID 37337030, 2023). "Directly inhibiting TLR2 with antagonists or addressing elements within the gut or tumor microbiota that trigger its activation using antimicrobial agents could potentially heighten the efficacy of certain anticancer treatments in tumors resistant to standard therapies." (PMID 38203626, 2023). "We then performed automated H-score analysis for TLR2 and IL-1β on identical tumor regions from consecutively stained sections and found a significant positive correlation between TLR2 and IL-1β expression, suggesting that TLR2 may regulate expression of the SASP in LUAD epithelium." (PMID 36351380, 2022). "The upregulation of TLR2 and CD247 in current work was significantly associated with the superior prognosis, suggesting that TLR2 and CD247 activation may be essential for anti-tumor immunity." (PMID 36389789, 2022). "However, MMP2 released by tumor cells may directly affect APCs or other cells within the TME that express TLR2 and TLR4." (PMID 34032639, 2021).
tumor (continued). "However, HMGB1 released from dying tumor cells may stimulate bone marrow-derived tumor-infiltrating myeloid dendritic cells through HMGB1/TLR2 signaling." (PMID 33669632, 2021). "The MyD88-dependent TLR2 signaling activates NF-κB pathway, which in turn stimulates the transcription of proinflammatory cytokines and chemokines, and may lead to cellular proliferation and tumor progression." (PMID 34715891, 2021). "The present data suggested a direct immunoregulatory activity of TLR2 signal to CD8+ T cells, and indicated that restrained TLR2 might be insufficient to induce functional cytotoxicity of CD8+ T cells, which was probably associated with tumor cells evasion and metastasis in GC patients." (PMID 34620075, 2021). "Moreover, most patients undergoing chemotherapy suffer from opportunistic infections, mostly from Gram-positive bacteria, and they display a diffusion of commensal bacteria to the tumor, which could further activate TLR2 on cancer cells." (PMID 33321934, 2020). "Therefore, significant activation of TLR2 during peritoneal infections or tumor growth could result in similar NK cell recruitment." (PMID 32696994, 2020). "Furthermore, inhibition of the HMGB1 or TLR2 signaling pathway was shown to slow tumor metastasis." (PMID 32943604, 2020). "However, TLR2 is also expressed on immune cells, such as Tregs, MDSCs, macrophages, and neutrophils, which can contribute to tumor growth and metastatic dissemination by stimulating the generation of an immunosuppressive microenvironment and of the metastatic niche." (PMID 33321934, 2020). "TLR2 agonist treatment to recruit NK cells, combined with additional components that activate NK cells (e.g. type I IFNs or IL‐12 and IL‐18), could potentiate NK cell‐mediated tumor clearance." (PMID 32696994, 2020). "Indeed, the Versican protein, released by tumor cells in the extracellular space, binds TLR2, activating multiple cell types in the tumor microenvironment, including myeloid, fibroblasts, and endothelial cells, and promotes the production of many proinflammatory cytokines." (PMID 33155039, 2020). "Therefore, several research groups addressed the question whether, in the tumor context, TLR2 can exert detrimental effects, promoting the suppression of effector T cell function." (PMID 33321934, 2020). "TLR6 functionally interacts with TLR2 to mediate the cellular response to bacterial lipoproteins and activate the NF-κB pathway and inflammatory events, and consequently, may contribute to tumor development and progression." (PMID 30388713, 2018). "After intravasation, most of tumor cells in circulation are damaged by the shear stress and mechanical stresses in blood, thus releasing intracellular molecules, many of which have been identified as the ligands for TLR2/4, including HMGB1, HSP60, HSP70, gp96, S100A8, S100A9, SAA3 and so on." (PMID 28415700, 2017). "Thus, targeting TLR2 in HNSCC appears to be an effective strategy to inhibit tumor growth in vivo." (PMID 25846753, 2015). "Extensive clinical investigation of BCG in patients with bladder cancer showed anti-tumor activity in the majority of them compared to intravesical doxorubicin chemotherapy, suggesting that TLR2 signaling may also contribute to the development of an anti-tumor immunity." (PMID 28548063, 2014). "The TLR2 expression profile of human CRC tissues revealed that high levels of TLR2 correlated with more advanced pathology grades and lymph node metastasis (N0, N1, N2) (***p < 0.001; **p < 0.01; *p < 0.05), suggesting an association between TLR2 expression and tumour progression." (PMID 23866094, 2013). "Positive TLR2 expression in the tumor microenvironment suggests that immune surveillance is activated against the altered epithelial cells, whereas TLR2 expression by malignant keratinocytes may be indicative of resistance to apoptosis as a prosurvival mechanism." (PMID 24376595, 2013).
tumor (continued). "Therefore, TLR2/4-activation may be still insufficient to generate highly immunogenic DC/tumor when producing high levels of TGF-β1." (PMID 23555011, 2013). "Taken together, the present studies demonstrated that tumor-derived autophagosomes (DRibbles) efficiently induced B cells activation, antibody production, cytokine secretion and antigen cross-presentation mainly depending on their protein component via TLR2/MyD88 dependent manner." (PMID 23326458, 2013). "Positive TLR2 expression in the microenvironment suggests that immune surveillance is activated against the altered cells, whereas TLR2 expression by malignant keratinocytes may correlate with apoptosis resistance and, hence, the survival of tumour cells." (PMID 21179035, 2011). "In addition to the increase in tumor multiplicity, TLR2-deficiency also led to significantly higher number of larger tumors (>1 mm2) (p<0.05) and higher tumor burden (nearly double) in TLR2−/− mice compared to WT mice (p<0.05)." (PMID 20885960, 2010). "Furthermore the intrabody strategy might be used to block TLR2 specific TNFα secretion of myeloid cells induced by factors secreted from tumour cells promoting metastasis." (PMID 20388199, 2010). "The therapeutic implications of these findings are demonstrated through both genetic deletion and pharmacological inhibition of TLR2 using AAV-mediated and antibody-based approaches in murine models, resulting in decreased tumor growth and extended survival." (PMID 41931634, 2026). "For example, Bifidobacterium pseudolongum promotes the polarization of TAMs toward M2 by acting on TLR2 and ILR5, while reducing TAM1, ultimately promoting tumor growth." (PMID 40102723, 2025). "Toll-like receptors (TLRs), including TLR2, TLR4, TLR7, TLR8, and TLR9, are critical pattern recognition receptors on TAMs, with diverse ligands such as tumor proteins, acute-phase proteins, drugs, and bacterial metabolites." (PMID 40948759, 2025). "Elevated expression of TLR1, TLR2, TLR4, TLR5, TLR6, and TLR9 has been detected in GBM, particularly within the mesenchymal subtype with significant impact in tumor progression." (PMID 41157253, 2025). "A previous study indicated that AKK, through the TLR2/NLRP3 signaling pathway, can induce the production of a significant amount of iNOS in M1-type TAM, thereby inhibiting tumor development." (PMID 41170411, 2025). "Meanwhile, TLR signaling, particularly through TLR2 and TLR4, is activated by microbial components and proinflammatory signals in the tumor microenvironment, recruiting adaptor proteins such as TNF receptor-associated factor 6 (TRAF6)." (PMID 41419456, 2025). "They bind to scavenger receptors and CD91, P2X purinoceptor 7 (P2RX7), and Toll-like receptor 2/4 (TLR2/4) on immature DCs respectively, facilitating the attraction and maturation of DCs capable of priming or reactivating tumor-specific T cells." (PMID 39987121, 2025). "Specifically, Hsp70, secreted by cancer cells, interacted with toll-like receptor 2 (TLR2) and triggered Mer receptor tyrosine kinase (MerTK) upregulation to stimulate MΦ M2 polarization and tumor growth." (PMID 39941817, 2025). "Genetic ablation of TLR2, TLR4, and TLR9 in K‐ras‐driven lung adenocarcinoma leads to a reduction of tumor burden, angiogenesis, and tumor cell proliferation." (PMID 40727252, 2025). "As discussed in Section 2 and Section 3, receptors such as TLR2, TLR4, TLR7, TLR9 and NLRP3 generally promote tumor progression and immune suppression." (PMID 41157253, 2025).